MUC2 (mucin 2, oligomeric mucus/gel-forming)
Diseases named in the same sentence as MUC2 in open-access papers (continued):
Sharing a sentence is not in itself a finding about the gene and the disease.
colitis (continued). "We observed that DSS-induced colitis in IEC AMPK KO mice led to a reduction in the number of colonic goblet cells, with a concomitant striking decrease in the expression of the major mucin-encoding gene Muc2 responsible for mucus synthesis." (PMID 35203241, 2022). "Interestingly, it has been recently shown that Muc2 mucin is essential in the maintenance of a “healthy” microbiota in mice, protecting them against chemical-induced colitis." (PMID 36699599, 2022). "A previous study demonstrated that knockout mice lacking the expression of Muc2 protein, which is produced by epithelial goblet cells and is the major component of intestinal mucin, developed spontaneous colitis, indicating that Muc2 played an important role in the protection of the gut barrier." (PMID 36139849, 2022). "Moreover, lower expression of MUC2 and acid mucins and higher levels of markers of colonic inflammation in WT+CPT-11 mice are consistent with the fact that the expression of MUC2 can be inversely correlated with the severity of inflammation." (PMID 35628140, 2022). "Altogether, the main behavioral traits characteristic to Muc2 colitis model are elevated novelty-induced locomotion and exploratory activity, reduced anxiety-related behaviors, weakened startle response and lack of behavioral discrimination between male and female animals." (PMID 36175462, 2022). "However, the expression of MUC2 was low in colitis due to the impaired goblet cells and reduced secretion of mucus." (PMID 36615796, 2022). "Consistent with the observation that HA administration increased the number of goblet cells and expression of MUC2 in colitis mice, transplantation from HA-treated colitis mice increased the mRNA levels of Muc1 and Muc2, as well as the protein expression of MUC2." (PMID 36558542, 2022). "Thus, it shows that MAS protects the integrity of the mucosal layer by inhibiting the down-regulation of Muc2 in the colon of DSS-induced colitis mice." (PMID 36139747, 2022). "Our experiment showed that DSS-induced colitis decreased the mRNA expressions of Occludin, ZO-1, E-cadherin, and MUC2 in colon tissue, which could be reversed by GC-K treatment." (PMID 36578000, 2022). "MUC2 is the primary component of the mucus barrier in the colon and is critical for protection against disease, as demonstrated in a classical model of MUC2 knockout mice spontaneously developing colitis." (PMID 35326394, 2022). "Furthermore, by inducing colitis in the mice colonized with phiEG37k together with its host bacteria, we demonstrate the enhancement of colonic MUC2 by the phage and its ameliorating effect on colitis." (PMID 34642357, 2021). "We found that the expression of Muc2 in the cecal epithelium was decreased by immunohistochemistry, which could protect the intestinal epithelial cells from spontaneous colitis." (PMID 34163442, 2021). "Consistently, A. muciniphila supplementation prevented colitis aggravation and strengthened colonic mucosal barriers in recipient mice by improving the expression of MUC2 and increased the number of goblet cells and MUC2-positive cells." (PMID 34722332, 2021). "Some phages could have colitogenic effects in colitis, while others have a role as exemplified in this study with phiEG37k, which is involved in the enhanced production of MUC2." (PMID 34642357, 2021). "Mice with DSS-induced colitis used in this study consistently showed decreased expression of ZO-1, occludin, MUC2, and MUC13, and elevated level of plasma LPS, indicating an impairment of intestinal barrier functions and thereby increased intestinal permeability." (PMID 33674694, 2021). "Concomitantly administrated CE at the high dose and sulfasalazine elevated the Muc2 mRNA level near 6-fold in comparison to the colitis group (p < 0.001), and the effect of combined treatment was even greater than the administration of CE or sulfasalazine alone (p < 0.05 in both cases)." (PMID 33299531, 2020).
colitis (continued). "Therefore, it is clear that MUC2 offers significant protection against colonic inflammation and that a well-maintained colonic mucus layer is vital in preventing murine colitis." (PMID 33013869, 2020). "Importantly, MUC2 expression is reduced in IBD in humans, and MUC2 deficiency causes intestinal inflammation, spontaneous colitis and gut dysbiosis in mice." (PMID 33328979, 2020). "We also assessed the main secretory mucin in the gut (Muc2), and a transmembrane mucin (Muc4) on the surface of intestinal epithelial cells, considering their importance both in experimental colitis and roles in postnatal intestinal mucus layer regulation related to microbial colonization." (PMID 32711559, 2020). "In this study, higher Muc-2 mRNA expression and higher number of goblet cells in the colon suggest that Bifidobacterium supplementation prevented mucosal damage, which otherwise was perturbed in colitis mice." (PMID 33122795, 2020). "It is very likely that similar events occur in vivo, however, further experiments including TJ immunoprecipitation from the appropriate cellular fractions followed by proteomic analysis are needed to understand the protein dynamics of the actomyosin and TJs in Muc2 knockout model of colitis." (PMID 33273633, 2020). "This indicates a down-regulation of MUC-2 expression in colitis compared to controls." (PMID 31198858, 2019). "Therefore, this study will investigate changes in MUC2 expression, inflammation, and changes in lectin expression in colitis patients." (PMID 31198858, 2019). "In this study, MUC-2 expression decreased significantly in colitis compared to controls." (PMID 31198858, 2019). "In parallel to the major constituent of the mucus layer Muc2, the multidrug resistance 1 (MDR1) and NEMO which have been established to be important for epithelial barrier function, loss of NR2F6 led to spontaneous colitis development in aged mice." (PMID 28779026, 2018). "The deficiency of cooperation of core 1 synthase (C1galt), which synthesizes the major constituent of the O-glycan core structure of the MUC2 protein, conduces to the disrupted mucus constitution and allows bacteria to invade the inner mucus layer, resulting in spontaneous colitis." (PMID 29619131, 2018). "DNBS-induced colitis was also characterized by an impairment of intestinal barrier function, as observed by evaluation of the different markers involved in the maintenance of epithelial integrity such as the mucins MUC-2 and MUC-3, occludin, and ZO-1." (PMID 28957373, 2017). "MUC2 was selected because it induces spontaneous colitis when knocked out in mice." (PMID 27490946, 2016). "Thus, spontaneous colitis in Muc2-/- mice monitored by neutrophil infiltration is most frequently observed in the distal colon and correlates with the influx of CD11bhiMHCII-/low cells." (PMID 26121642, 2015). "Moreover, the data suggest that P3 iMPs have a role in initial colitis confined distally while P2 DCs play a role in driving colitis in Muc2-/- mice that spreads proximally." (PMID 26121642, 2015). "Indeed, changes in the local cytokine environment in the colon, such as that induced by commensal bacterial penetration due to a defective mucus barrier in Muc2-/- mice, influences iMP function and tips the homeostatic balance towards colitis." (PMID 26121642, 2015). "To investigate whether aberrant expression of miRNAs are involved in colitis malignant transformation, we isolated the colonic epithelial cells from 3-month old mice (4 Muc2−/− mice and 4 Muc2+/+ mice) and conducted miRNA profiling." (PMID 24941171, 2014). "Previous studies found that Muc2 and Tff3 genes were up-regulated during colitis induction, and suggested that their mRNA levels could be used as early markers of inflammation." (PMID 24416230, 2014).
colitis (continued). "These mice are completely (Muc2-/−) or partially deficient in gel-forming Muc2 protein (C3GnT) and spontaneously develop colitis and later colorectal tumors, in addition to being more susceptible to DSS-induced colitis." (PMID 23977158, 2013). "Moreover, MUC2−/− mice spontaneously develop colitis, indicating that MUC2 is essential for the protection of the colon." (PMID 24367242, 2013). "A role for Muc2 in the suppression of colorectal carcinoma has also been suggested because Muc2 knockout (KO) mice spontaneously develop colitis and adenomas that progress to invasive adenocarcinoma, suggesting an important function for this mucin in colonic protection." (PMID 20138044, 2010). "However, similar to our findings in murine C. rodentium infection, a reduction in MUC2 expression occurs in UC adjacent to ulceration and in active colitis, and MUC1 expression was upregulated in severe UC at the site of rupture of crypt abscesses." (PMID 19088856, 2008). "However, the expression of MUC-2 was significantly increased after administration of probiotic; these results are consistent with previous experimental results, which suggested that probiotics can alleviate mucosal damage in colitis." (PMID 38613088, 2024). "That is to say, GQDs and GOQDs can directly adhere on and cover the active site of AGR2 protein, which may inhibit the normally physiological binding of AGR2 active site to MUC2 (a direct involvement of AGR2 in mucin processing), finally heightening susceptibility to colitis." (PMID 38528032, 2024). "The expression of major structural mucus components including MUC2 is reduced in active UC, and MUC2‐deficient mice do not secrete any mucus, have bacteria in direct contact with the epithelium and spontaneously develop colitis." (PMID 36440681, 2023). "Furthermore, the present findings also showed that MT supplementation could alleviate LPS-induced colitis and the reduction of goblet cells and MUC2 protein, Villin, and Tff3 mRNA." (PMID 35355860, 2022). "Therefore, we speculated that MT could improve colitis by suppressing Aeromonas-goblet cell interactions, thereby upregulating the goblet cells number and MUC2 protein, further improving SD-induced colitis." (PMID 35355860, 2022). "As microbiota transfer partially reconstitutes behavioral traits in the wild-type littermates in the absence of inflammation, we proposed that metabolomic changes induced by intestinal microbes might mediate the gut-brain interaction in the Muc2 model of colitis." (PMID 36175462, 2022). "The enhancement of MUC2 production in the colonic epithelial cells from phiEG37k-colonized mice may account for the ameliorating effect of the phiEG37k phage in this colitis model." (PMID 34642357, 2021). "Thus, MUC-2 loss-mediated mucosal barrier impairment is a causal factor rather than a consequence of colitis and CAC vulnerability in Golm1−ΔIEC mice." (PMID 33850109, 2021). "In addition to MUC2, there are other mucins that are important for protection from colitis." (PMID 33502317, 2021). "Similarly, DSC also induced muc‐2 mRNA expression in experimental colitis." (PMID 32945118, 2020). "Thus, although the mechanism of MUC2 induction by IL-18 remains unknown, this stimulatory effect of IL-18 on MUC2 expression via CDX-2 upregulation seems to contribute to alleviation of colitis." (PMID 27966619, 2016). "In a MUC2-deficient mouse model, mice lacking MUC2 were found to develop spontaneous colitis." (PMID 28074093, 2016). "For example, strain ZDY2013, when combined with isomaltooligosaccharides, enhances the expression of MUC2, tight junction proteins (ZO-1, claudin), and cytokines such as IL-10 and IL-22 in DSS-induced colitis models." (PMID 41141596, 2025). "HPE treatment improved all assessed morphological parameters compared to the untreated group and also restored the expression of MUC‐2 in the goblet cells, which was significantly reduced in DSS‐induced colitis." (PMID 41165567, 2025).
colitis (continued). "In a DSS (dextran sulfate sodium)‐induced colitis mouse model, IPA promotes Muc2 gene expression through PXR, enhancing mucin secretion." (PMID 40103267, 2025). "We found that treatment with A. shahii significantly increased the mRNA expression of mucus gene Muc2, which was decreased in DSS-induced colitis mice." (PMID 39936902, 2025). "According to our data, DSS treatment significantly reduced the expression of MUC2 and MUC5AC, whereas APS-H alleviated DSS-induced colitis and increased the expression of mucins." (PMID 41010526, 2025). "In experimental colitis models, the induction of DSS destroys cuprocytes, reduces Muc2 mRNA expression, decreases the thickness of the mucus layer in the intestine, and increases the permeability of the intestine to bacteria." (PMID 40430964, 2025). "In parallel, the mRNA expression of Muc2, ZO-1, Occludin and Claudin4 were markedly reduced in the DSS-induced colitis mice (p < 0.05)." (PMID 40130239, 2025). "Lactobacillus rhamnosus GG postbiotic HM0539 enhanced mucin 2 (MUC2) and zonula occludens-1 (ZO-1) expression and prevented dextran sodium sulfate (DSS)-induced colitis." (PMID 40219029, 2025). "To further investigate the role of fucosylation-mediated MUC2 in the maintenance of colitis, we tested the effect of l-fucose supplementation, an essential substrate of fucosylation, in a DSS-induced colitis model." (PMID 38979515, 2024). "Supplementation with SBP significantly restored the levels of ZO-1, occludin, Muc2, Muc3, and CDX2 in the colon of colitis mice, approaching near-normal levels." (PMID 38732527, 2024). "The mRNA expression of MUC2, which is a crucial element of the mucus barrier, was observed to be downregulated in mice having DSS colitis, demonstrating UC induced mucosal barrier damage and was significantly upregulated in the DP group." (PMID 38601942, 2024). "In C. rodentium-induced colitis mice, the inclusion of 0.5% AKG in drinking water mitigated goblet cell dysfunction and restored mRNA amounts of Mucin 2 (Muc2) and Muc3." (PMID 38438107, 2024). "Our findings demonstrate that SC-4 can colonize germ-free (GF) mice, increasing mucin thickness by activating MUC-1 and MUC-2 genes, thereby protecting GF mice from Dextran Sodium Sulfate (DSS)-induced colitis." (PMID 39069899, 2024). "Deletion of mesenchymal COX suppressed this process and impaired the expression of Muc2 and aggravated DSS-induced colitis in vivo." (PMID 37574502, 2023). "In DSS colitis in Muc2+/+ during the acute and restitutive phases of DSS colitis, even though Muc2 mRNA expression was low, Fcgbp mRNA was high with increased protein expression on day 15 as compared to Muc2-/- littermates and was associated with restitution." (PMID 37359538, 2023). "Our results showed that DSF+Cu2+ had a protective effect on DSS-induced colitis, manifested by significantly improved body weight, colonic length, histological score, reduced DAI score, and increased expression of MUC2, ZO-1 and occludin." (PMID 37284442, 2023). "In contrast to Muc2 and Muc3, higher Muc1 expression was detected in mice with DSS-induced colitis but was reduced by the EV treatment." (PMID 37966243, 2023). "Along the same lines, B. dentium was also shown to increase MUC2, limit goblet cell reduction, and improve the mucus layer in a TNBS-induced model of colitis." (PMID 38045921, 2023). "Pretreatment with IL-18 reduced inflammatory infiltration and increased the MUC2 and TFF-3 production in mice with dextran sulfate sodium-induced colitis." (PMID 37383609, 2023). "Several genetic mouse models with profound mucus layer permeability, such as MUC2, NHE3, and C1GALT1 knock‐out mice, developed colitis." (PMID 37691494, 2023). "Overall, our study revealed that MT2-mediated MT suppressed Aeromonas coupling with goblet cells and restored MUC2 depletion by inhibiting the TLR4/MyD88/GSK-3β/β-catenin/ROS/NF-κB loop, ultimately improving SD-induced colitis in mice." (PMID 35355860, 2022).
colitis (continued). "Indeed, CDX2 is a positive regulator of the Muc2 and Trefoil Factor 3 (TFF3) genes involved in the production and stabilization of the mucus layer, respectively, and whose deficiency induces hypersensitivity to chemically-induced colitis (such as that induced by dextran sulfate sodium (DSS))." (PMID 35203499, 2022). "In DSS-induced colitis, treatment with MRS2211 significantly increased the expression of ZO-1 and MUC-2." (PMID 35982893, 2022). "The current study found that at day 46, DSS-induced colitis resulted in a significant decrease in KI67, MUC2, ZO-1, and Occluding mRNA expression in the colon tissues." (PMID 35935215, 2022). "Consistently, by contrast to control mice, significant decreases in colonic mucus and tight junction proteins (MUC2 and ZO-1) were observed in DSS-colitis mice, and C. butyricum-derived EVs upregulated the expression level of gut barrier related-proteins." (PMID 35578339, 2022). "Our results demonstrated that melatonin-mediated MT2 inhibits Aeromonas-goblet cell interactions to restore the level of MUC2 production via LPS/TLR4/MyD88/GSK-3β/ROS/NF-κB loop, further improving colitis in SD mice." (PMID 35355860, 2022). "Both ZO-1 and MUC-2 displayed a decreasing trend in the DSS group, which meant these two proteins weakened in the colitis body." (PMID 36570170, 2022). "The expression of MUC2, the major component of the mucus barrier, was increased in DSS-induced colitis at the mRNA level." (PMID 34658866, 2021). "Our experiment showed that DSS-induced colitis decreased the mRNA expression of KLF4, MUC2 and ZO-1 in colon tissue." (PMID 34675239, 2021). "We found NR2F6 binding to the −2 kb region of the Muc2 promoter in healthy colons; however, binding capability was found to be reduced under inflammatory DSS colitis conditions." (PMID 28779026, 2018). "When investigating the effect of MMP-9 on the colonic epithelial barrier in a model of colitis, it was found that MMP-9−/− mice had increased goblet cell numbers and increased MUC2 expression." (PMID 25948887, 2015). "Compared to the normal group, the colitis mice exhibited significantly increased mRNA expression levels of epithelial barrier proteins (CLDN-2, occludin, and ZO-1) as well as the mucin barrier protein (MUC2) in their colon tissues." (PMID 40529132, 2025). "Given the previous findings on body weight, DAI scores, colon length, and intestinal barrier damage, all of which indicated that APS alleviated DSS-induced colitis in a dose-dependent manner, we selected mice in the APS-H group to detect the expression of MUC2 and MUC5AC." (PMID 41010526, 2025). "The SVHRSP treatment increased tight junction protein expression, protected the goblet cells and the secretion of MUC2, and reduced intestinal permeability, suggesting that SVHRSP could potentially inhibit colitis by restoring intestinal integrity." (PMID 41300453, 2025). "The late onset of moderate inflammation in the absence of Muc17 contrasted acute induction of severe colitis in C3GnT–/–, Vamp8–/–, and Tgm3–/– mice with defects in Muc2 glycosylation, secretion, and cross-linking." (PMID 39699961, 2024). "As illustrated in the heatmap, there were three genes that were significantly downregulated by colitis induction (TNBS + Veh) and restored after disease mice were treated with I3C (TNBS + I3C), which included one mucin protein (Muc2) and two goblet cell markers (Tff1 and Tff3)." (PMID 38397081, 2024). "Additionally, in an acute colitis prevention mouse model, prophylactic MFGM treatment resulted in an upregulation in Muc2 and Muc4 gene expression." (PMID 38612988, 2024). "Select mucins from in vivo experimental WT and AhRΔIEC colitis mice treated with or without I3C were validated in CECs, which included Muc1, Muc2, and Muc3." (PMID 38397081, 2024).